TMEM109 (transmembrane protein 109)
Description:
Functions as a voltage-gated monoatomic cation channel permeable to both potassium and calcium (By similarity). Plays a role in the cellular response to DNA damage.
Synonyms: Mg23; MGC5508; SND3; hSND3
Tractability: Antibody: UniProt predicts a signal peptide or a membrane-spanning region. PROTAC: ubiquitination databases record sites on it; its protein half-life has been measured.
Gene: Protein-coding gene on chromosome 11 (60,912,521 to 60,923,443, forward strand). Ensembl gene ENSG00000110108.
Subcellular location: Nucleus outer membrane; Endoplasmic reticulum membrane; Sarcoplasmic reticulum membrane
Subcellular location (Human Protein Atlas): Endoplasmic reticulum; Nuclear membrane; Actin filaments; Vesicles
Gene Ontology:
Molecular function: protein binding; voltage-gated monoatomic cation channel activity
Biological process: cellular response to gamma radiation; negative regulation of programmed cell death; monoatomic cation transmembrane transport
Cellular component: extracellular exosome; endoplasmic reticulum membrane; nuclear outer membrane; sarcoplasmic reticulum membrane
Genetic constraint (gnomAD): Loss-of-function variants: 19 observed, 27.55 expected, observed/expected ratio (o/e) 0.69, 90% interval 0.48 to 1.01. The upper end of that interval is the gene's LOEUF score, 1.01, which puts it in group 4 of 6, group 1 being the genes least tolerant of losing a copy. Missense variants: 262 observed, 317.14 expected, observed/expected ratio (o/e) 0.83, 90% interval 0.75 to 0.92. Synonymous variants: 129 observed, 148.97 expected, observed/expected ratio (o/e) 0.87, 90% interval 0.75 to 1.
Homologues: Orthologues: chimpanzee TMEM109 (99% identical), macaque TMEM109 (96% identical), rabbit TMEM109 (88% identical), dog TMEM109 (86% identical), guinea pig TMEM109 (76% identical), mouse Tmem109 (75% identical), rat Tmem109 (74% identical), pig TMEM109 (67% identical), zebrafish si:dkey-9i23.15 (22% identical).
Diseases named in the same sentence as TMEM109 in open-access papers:
TMEM109 is named in the same sentence as 11 diseases in open-access papers, as found by Europe PMC text mining. Sharing a sentence is not in itself a finding about the gene and the disease. The quoted sentences say what the papers report.
myeloid leukemia (1 paper, 2025). A clonal proliferation of myeloid cells and their precursors in the bone marrow, peripheral blood, and spleen. "Consistent with MG23’s role in cellular fate, TMEM109, the gene encoding MG23, has been raised as a gene biomarker for pancreatic head cancer and myeloid leukemia by recent studies." (PMID 41439978, 2025).
cancer (1 paper, 2023). A tumor composed of atypical neoplastic, often pleomorphic cells that invade other tissues. "ZDHHC5 has been implicated in other cancers, while TMEM109 is involved in regulating apoptosis." (PMID 37756103, 2023).
tumor (1 paper, 2025). "MYBPC2, TMEM109, and LACM3 have also been associated with various tumor types." (PMID 41009814, 2025).
TMEM109 also shares sentences with these, for which no sentence is quoted: heart failure (2 papers); bladder cancer (1); breast carcinoma (1); chronic heart failure (1); infection (1); muscle disorders (1); Obesity (1); renal carcinoma (1).